SDHC (succinate dehydrogenase complex subunit C)
Description:
Membrane-anchoring subunit of succinate dehydrogenase (SDH) that is involved in complex II of the mitochondrial electron transport chain and is responsible for transferring electrons from succinate to ubiquinone (coenzyme Q). SDH also oxidizes malate to the non-canonical enol form of oxaloacetate, enol-oxaloacetate (By similarity). Enol-oxaloacetate, which is a potent inhibitor of the succinate dehydrogenase activity, is further isomerized into keto-oxaloacetate (By similarity).
Synonyms: QPs1; CYBL; CYB560; SDH3; PGL3; PPGL3
Tractability: Small molecule: a structure with a bound ligand is known. Antibody: UniProt predicts a signal peptide or a membrane-spanning region. PROTAC: ubiquitination databases record sites on it; its protein half-life has been measured.
Chemical probes: TTT20171
Gene: Protein-coding gene on chromosome 1 (161,314,381 to 161,363,206, forward strand). Ensembl gene ENSG00000143252.
Subcellular location: Mitochondrion inner membrane
Pathways (Reactome):
Metabolism: Citric acid cycle (TCA cycle); Maturation of TCA enzymes and regulation of TCA cycle; Respiratory electron transport
Gene Ontology:
Molecular function: protein binding; heme binding; electron transfer activity; succinate dehydrogenase (quinone) activity
Biological process: aerobic respiration; mitochondrial electron transport, succinate to ubiquinone; proton motive force-driven mitochondrial ATP synthesis; tricarboxylic acid cycle
Cellular component: mitochondrial inner membrane; mitochondrion; respiratory chain complex II (succinate dehydrogenase); membrane; mitochondrial matrix
Genetic constraint (gnomAD): Loss-of-function variants: 9 observed, 17.6 expected, observed/expected ratio (o/e) 0.51, 90% interval 0.31 to 0.89. The upper end of that interval is the gene's LOEUF score, 0.89, which puts it in group 3 of 6, group 1 being the genes least tolerant of losing a copy. Missense variants: 128 observed, 186.54 expected, observed/expected ratio (o/e) 0.69, 90% interval 0.59 to 0.8. Synonymous variants: 71 observed, 71.01 expected, observed/expected ratio (o/e) 1, 90% interval 0.82 to 1.22.
Gene-disease validity (ClinGen):
ClinGen rates the evidence that SDHC causes each of these diseases.
hereditary pheochromocytoma-paraganglioma (autosomal dominant): Definitive. Neoplasm predisposition characterized by an increased risk of paragangliomas (tumors that arise from neuroendocrine tissues distributed along the paravertebral axis from the base of the skull to the pelvis) and pheochromocytomas (paragangliomas that are confined to the adrenal medulla).
mitochondrial disease (inheritance undetermined): No Known Disease Relationship.
Homologues: Orthologues: chimpanzee SDHC (100% identical), dog SDHC (90% identical), pig SDHC (89% identical), guinea pig SDHC (85% identical), rat Sdhc (82% identical), mouse Sdhc (80% identical), tropical clawed frog sdhc (75% identical), zebrafish sdhc (61% identical), rabbit SDHC (57% identical), macaque SDHC (53% identical), Drosophila melanogaster SdhCL (34% identical), Caenorhabditis elegans mev-1 (31% identical).
Diseases named in the same sentence as SDHC in open-access papers:
SDHC is named in the same sentence as 96 diseases in open-access papers, as found by Europe PMC text mining. Sharing a sentence is not in itself a finding about the gene and the disease. The quoted sentences say what the papers report.
paraganglioma (58 papers, 2005 to 2025). A benign or malignant neoplasm arising from paraganglia located along the sympathetic or parasympathetic nerves. "Germline variants in SDHC are more rarely associated with the development of paragangliomas/pheochromocytomas than variants in SDHB or SDHD." (PMID 30871634, 2019). "However, ovarian cancer is an atypical cancer phenotype with SDHC, which is typically associated with a risk for pheochromocytoma and paraganglioma." (PMID 41465149, 2025). "Extra-adrenal paraganglioma was present in one case with SDHC biallelic variants." (PMID 38473309, 2024). "Furthermore, the SDHC gene has also been linked to gastrointestinal stromal tumor and paraganglioma, although these variants are potential pathogenic factors." (PMID 38808331, 2024). "About 4% of paraganglioma patients carry mutations in the SDHC gene." (PMID 24899893, 2014). "Based on recent lineage tracing studies, we hypothesized that conditional SDHC loss in early embryogenesis during migration of primordial neural crest cells that form the susceptible chromaffin cells of the adrenal medulla might induce paraganglioma." (PMID 39399478, 2024). "Furthermore, in a 2016 study, a large sample set of 95 patients was investigated, in which 84 had succinate dehydrogenase-deficient GIST caused either by SDH mutations (75%) or by SDHC promoter hypermethylation (25%), and 18 were syndromic GISTs with chondromas and/or paragangliomas." (PMID 36980917, 2023). "In comparison, the PGL3 syndrome related to mutations in the SDHC gene consists of an autosomal dominant disease that is most often characterized by benign head and neck paragangliomas, although in rare cases paragangliomas/pheochromocytomas may occur in other body parts as well." (PMID 28187001, 2017). "Wild type GIST driven by germline mutations in SDHB, SDHC, or SDHD subunits is a component of the Carney-Stratakis syndrome, an inherited predisposition syndrome characterized by the presence of GIST and paraganglioma." (PMID 36980917, 2023). "Overall, patients with SDHA-mutant tumors tend to have an older median age compared to the SDH-deficient GISTs due to other subunit mutations, while SDHB, SDHC, and SDHD mutant GISTs usually also develop paragangliomas." (PMID 36980917, 2023). "Germline mutations in SDHA, SDHB, SDHC, and SDHD (collectively, SDHx) are associated with the development of PRL- and GH-secreting adenomas, pheochromocytomas, and/or paragangliomas, a syndrome named 3P association." (PMID 35743266, 2022). "Germline mutations in SDHx are a major cause of phaeochromocytoma and paragangliomas but inheritance patterns and risks differ between genes, and the penetrance of germline SDHA mutations is much lower than for SDHB, SDHC or SDHD." (PMID 35441217, 2022). "Germline mutation of the succinate dehydrogenase subunit genes, SDHA, SDHB, SDHC or SDHD, is associated with increased risk for paraganglioma (PGL), pheochromocytoma (Pheo), gastrointestinal stromal tumor (GIST) and renal cell carcinoma." (PMID 36455002, 2022). "Other rare epigenetic events involve the recurrent aberrant DNA methylation of SDHC seen in GIST associated to the Carney triad (CT), which is a rare condition with synchronous or metachronous occurrence of GIST, paragangliomas, and pulmonary chondromas." (PMID 35059314, 2021). "Approximately 20% of patients diagnosed with a phaeochromocytoma or paraganglioma carry a germline mutation in one of the succinate dehydrogenase (SDHx) genes (SDHA, SDHB, SDHC and SDHD), which encode the four subunits of the SDH enzyme." (PMID 34021277, 2021). "CSS by definition is due to SDHB, SDHC, and SDHD mutations and is characterized by the combination of GIST and paraganglioma inherited in an apparently autosomal dominant manner and with incomplete penetrance." (PMID 35059314, 2021). "Another study on SDHB, SDHC, and SDHD gene mutation analysis in a large cohort of patients with a personal or family history of paragangliomas/pheochromocytomas was performed." (PMID 32948182, 2020).
paraganglioma (continued). "VHL, RET, NF1, SDHB, and SDHD are major susceptibility genes, accounting for 90% of familial pheochromocytomas/paragangliomas, whereas TMEM127, SDHA, SDHC, SDHAF2, and MAX are minor susceptibility genes responsible for 10% of these tumors." (PMID 30456751, 2018). "The prevalence of germline mutations in SDHB, SDHC, SDHD, VHL and MAX in PCC and paraganglioma patients is, respectively, 10%, 1%, 9%, 7%, and 1%." (PMID 29768630, 2018). "Germline mutations in the four genes encoding SDH subunits (SDHA, SDHB, SDHC and SDHD) are linked to the development of neuroendocrine tumors such as pheochromocytomas and paragangliomas." (PMID 28911113, 2017). "Mutations in the CII subunit genes SDHA, SDHB, SDHC and SDHD have also been associated with paragangliomas and pheochromocytoma." (PMID 26839416, 2016). "Here, we examine the SDHB, SDHC, and SDHD mutation spectrum in the Danish population by screening of 143 Danish pheochromocytoma and paraganglioma patients." (PMID 27279923, 2016). "Germline mutations in the succinate dehydrogenase complex genes SDHB, SDHC, and SDHD predispose to pheochromocytomas and paragangliomas." (PMID 27279923, 2016). "Heterozygous germline mutations in SDHA, SDHB, SDHC, and SDHD cause hereditary paragangliomas and pheochromocytomas, and germline mutations in SDHB and SDHC were found to be associated with gastrointestinal stromal tumors." (PMID 22995659, 2012). "Previous studies demonstrated that SDHB-, SDHC-, and SDHD-related paragangliomas and GIST all show loss of SDHB immunohistochemical expression." (PMID 22974104, 2012). "Added to that, germline mutations in the mitochondrial succinate dehydrogenase (complex II of the oxidative phosphorylation chain) subunits SDHD, SDHC, and SDHB are a frequent cause of paragangliomas of the head and neck and of phaeochromocytomas." (PMID 21541025, 2011). "Germline mutations of the tumor suppressor genes SDHB, SDHC and SDHD play a major role in hereditary paraganglioma and pheochromocytoma." (PMID 19368708, 2009). "Subsequently, two other subunits of SDH, SDHC (chromosome 1q21), and SDHB (chromosome 1p36) were implicated in paragangliomas." (PMID 19956719, 2009). "In contrast to paraganglioma in SDHB and SDHC-linked families, both located on chromosome 1, in SDHD-linked families and in the recently described SDH5 (SDHAF2) family, only a mutation inherited via the paternal line results in tumorigenesis." (PMID 19956719, 2009). "Here we report the analysis of the SDHB and SDHC genes in this group of patients and in addition the analysis of 5 families presenting with pheochromocytoma and/or paraganglioma." (PMID 16405730, 2006). "Paraganglioma (PGL) is often linked with MEN, and its occurrence is commonly associated with metabolism-related mutation genes, which currently include SDHA, SDHB, SDHC, SDHD, and SDHAF2." (PMID 39591360, 2024). "Similarly, paragangliomas, pheochromocytomas and GISTs associated with germline mutation of SDHB, SDHC and SDHD have been previously shown to exhibit CIMP in comparison to tumors caused by mutations in other genes." (PMID 36455002, 2022). "This aggregate result underscores the different tumor spectrum of SDHA-germline variant carriers and Carney Stratakis Syndrome patients, which are known to harbor SDHB, SDHC, or SDHD mutations, and to develop invariably the association of GIST and paraganglioma during their life course." (PMID 35059314, 2021). "SDHAF2 mutations may present similarly to mutations in SDHA, SDHB, SDHC and SDHD as paraganglioma and pheochromocytoma." (PMID 26839416, 2016).
paraganglioma (continued). "Strikingly, inactivating germline mutations in SDHB or SDHC genes have been also identified in sporadic WT GISTs occurring in patients without a personal or family history of paraganglioma." (PMID 22974104, 2012). "In conclusion, these data indicate that germline mutations of SDHB and SDHC play a minor role in sporadic head and neck paraganglioma and further underline the importance of germline SDHB mutations in cases of familial pheochromocytoma-paraganglioma." (PMID 16405730, 2006). "Interestingly, Carney-Stratakis syndrome, characterized by germline mutations in SDHB, SDHC, or SDHD, is a hereditary syndrome associated with GIST and paraganglioma, and may also be associated with SDH-mutant RCC." (PMID 40018405, 2025). "Carney-Stratakis syndrome (CSS), a rare condition characterized by paragangliomas and/or pheochromocytomas and gastrointestinal stromal tumors (GIST), is caused by germline heterozygous pathogenic variants in the succinate dehydrogenase subunit genes (SDHB, SDHC, SDHD)." (PMID 40242210, 2025). "For one female patient with a history of paraganglioma, pulmonary hamartomas, and SDH-deficient GIST (as determined by SDHB loss in the immunohistochemistry analysis), and no detectable germline variant, somatic methylation analysis detected biallelic hypermethylation of the SDHC promoter." (PMID 39594770, 2024). "Based on the totality of this evidence, the germline SDHC:c.374T>G variant, previously classified as VUS by the clinical laboratory, was classified as presumed deleterious and treated as a clinically significant finding in relation to hereditary paraganglioma in this patient." (PMID 36091175, 2022). "In addition to their role in primary mitochondrial disease, heterozygous germline variants in other complex II subunits and assembly factors (including SDHA, SDHB, SDHC, SDHD and SDHAF2) are associated with paragangliomas, phaeochromocytomas and gastrointestinal stromal tumours." (PMID 34012134, 2021). "Furthermore, among the conditions related to mutations in the SDHx genes, the Carney diad (or Carney-Stratakis diad) syndrome is associated with mutations in the SDHB, SDHC, and SDHD genes and manifests as paragangliomas and gastrointestinal stromal tumors in patients of either sex." (PMID 28187001, 2017). "Recurrent epimutations of SDHC have been identified in GIST and Carney triad (a syndrome characterized by paraganglioma, GIST and pulmonary chondroma)." (PMID 34021277, 2021). "SDHA, SDHAF2, SDHB, SDHC, SDHD, MAX, and TMEM127 genes are offered to be analyzed for the diagnosis of paraganglioma/pheochromocytoma (PGL/PCC) syndromes." (PMID 33777662, 2021). "For instance, a combination of papillary thyroid carcinoma and paraganglioma in the same patient revealed alterations in PTEN and SDHC genes, leading to Cowden syndrome and pheochromocytoma–paraganglioma diagnosis." (PMID 28402931, 2017). "Paragangliomas may be hereditary and can be associated with familial paraganglioma, neurofibromatosis type 1, von Hippel-Lindau disease, the Carney triad, multiple endocrine neoplasia type 2, and mutations of the succinate dehydrogenase genes (SDHB, SDHC, and SDHD)." (PMID 17683569, 2007). "In this study, we investigated a woman who presented with pheochromocytoma, paraganglioma, and GIST, fulfilling the criteria for CSS but lacking pathogenic variants or gene deletions in the SDHB, SDHD, or SDHC genes." (PMID 40242210, 2025). "The syndromic presentation of HNPGLs is associated with mutations in SDHD (paraganglioma syndrome type 1, PGL1), SDHAF2 (PGL2), SDHC (PGL3), SDHB (PGL4), SDHA (PGL5), VHL (von Hippel–Lindau syndrome), HIF-2α (paraganglioma–somatostatinoma–polycythemia), and NF1 (neurofibromatosis type 1 syndrome)." (PMID 39684472, 2024). "The scarcity of SDHAF2 mutations was reinforced by the failure to document mutations in this gene among 315 patients with paraganglioma and without mutations in the SDHD, SDHC, or SDHB genes." (PMID 24899893, 2014).
paraganglioma (continued). "While reports of reduced penetrance for the NM_003001.5:c.377A>G; p.(Tyr126Cys) variant in SDHC (HGNC:10682) were not identified, this variant is relatively rare in pheochromocytoma/paraganglioma cohorts but has the highest gnomAD Grpmax FAF for ClinVar SDHC P/LP variants." (PMID 41000626, 2025). "In a study of 34 patients with sporadic WT GISTs without a family history of paraganglioma, 12% of patients were found to have germline mutations in SDHB or SDHC, while those who did not harbor a detectable SDH mutation demonstrated significantly decreased SDHB protein expression." (PMID 30456751, 2018). "We could not include other paraganglioma genes like SDHA, SDHC, MAX, etc., and we did not include NF1 carrier cases in this study." (PMID 33777662, 2021).
pheochromocytoma (48 papers, 2005 to 2025). "SDHC epimutations are more commonly implicated in SDH‐deficient GIST compared to SDH‐deficient paraganglioma/pheochromocytoma and are almost exclusively identified in female patients." (PMID 39927693, 2025). "The complexity of SDH‐deficient GISTs, including their association with hereditary syndromes such as Hereditary Paraganglioma‐Pheochromocytoma and/or hypermethylation of the SDHC promoter, underscores the need for comprehensive germline testing." (PMID 39927693, 2025). "SDHC mutation has been confirmed to be associated with various cancers, such as kidney cancer, gastrointestinal stromal tumors, pheochromocytoma, and head and neck paraganglioma." (PMID 32156290, 2020). "Germline mutations of the SDHD, SDHB and SDHC genes, encoding three of the four subunits of succinate dehydrogenase, are a major cause of hereditary paraganglioma and pheochromocytoma, and demonstrate that these genes are classic tumor suppressors." (PMID 16405730, 2006). "Isolated deletion of SDHB caused an obesity phenotype that was similar to SDHC deletion, and codeletion of SDHB and NF1 resulted in development of SDHB‐deficient pheochromocytomas." (PMID 39399478, 2024). "Genomic analysis of familial PGL/pheochromocytoma (PCC) has shown that while mutations of SDHD and SDHC are associated with PGL1 and PGL3, mutations in the large subunit genes SDHB, SDHA and SDHAF2 are associated with PGL4, PGL5 and PGL2." (PMID 35382567, 2022). "Our findings are in line with increased ROS levels in the mitochondria of SDHB-deficient mouse phaeochromocytoma cells, confirmed by two SDHB-silenced cell lines and one SDHC-mutated transgenic mouse cell line." (PMID 34680273, 2021). "Familial CPGLs occur as hereditary paraganglioma/pheochromocytoma (PGL/PCC) syndromes, including PGL1, PGL2, PGL3, PGL4, and PGL5, which are associated with germline mutations in the SDHD, SDHAF2, SDHC, SDHB, and SDHA genes, respectively." (PMID 32971818, 2020). "SDHB and SDHD mutations are common in pheochromocytoma/paraganglioma, and SDHA mutations and SDHC promoter hypermethylation are relatively common in GISTs4." (PMID 30971719, 2019). "In face of the malignant presentation, molecular studies were conducted to screen mutations in five genes related to pheochromocytoma: SDHB, SDHD, SDHC, MAX and VHL." (PMID 29768630, 2018). "Germline mutations in the succinate dehydrogenase (SDHA, SDHB, SDHC, SDHD, SDHAF2) or Von Hippel-Lindau (VHL) genes cause hereditary paraganglioma/pheochromocytoma." (PMID 28099933, 2017). "These syndromes involve a group of rare autosomal dominant disorders affecting sympathetic and parasympathetic paraganglia, caused by germline mutations of the genes SDHB, SDHC and SDHD, although some of these mutations can also be detected for patients with apparently sporadic pheochromocytomas." (PMID 23360571, 2013). "The major mutations associated with pheochromocytoma are von Hippel-Lindau gene (VHL), REarranged during Transfection (RET) proto-oncogene, neurofibromatosis type 1 gene (NF1), genes encoding four succinate dehydrogenase complex subunits (SDHx; i.e., SDHA, SDHB, SDHC, and SDHD genes)." (PMID 35932074, 2022). "Familial HNPGLs together with pheochromocytomas (PCCs) account for about 40% and are associated with four types of hereditary paraganglioma syndromes (PGL1–5) caused by mutations in the following genes: SDHD (PGL1), SDHAF2 (PGL2), SDHC (PGL3), SDHB (PGL4), and SDHA (PGL5)." (PMID 33391357, 2020). "Though this relationship is not specifically related to a germline variant, RET, SDHB, SDHC, SDHD, and SDHAF2 each include a predisposition of developing pheochromocytoma and thus must be considered." (PMID 35685436, 2022).